SHBG (sex hormone binding globulin)
Diseases named in the same sentence as SHBG in open-access papers (continued):
Sharing a sentence is not in itself a finding about the gene and the disease.
Insulin resistance (continued). "In patients with PCOS, SHBG concentrations are usually low because of elevated androgen levels, and hyperandrogenemia promotes compensatory hyperinsulinemia and insulin resistance by increasing lipoprotein and reducing insulin clearance." (PMID 35615684, 2022). "Lifestyle changes not only have a direct effect on SHBG as a hepatokine but also a metabolic effect on the de novo lipogenesis pathway (intrahepatic accumulation of lipids and insulin resistance), of which SHBG is a biomarker." (PMID 36235799, 2022). "Insulin and androgens work synergistically to reduce SHBG levels, resulting in higher free androgen levels, which aggravates the insulin resistance." (PMID 36140452, 2022). "Serum free testosterone is higher than total testosterone, especially in PCOS, who commonly have reduced SHBG levels, mainly due to insulin resistance." (PMID 35456928, 2022). "The increased insulin level, a compensatory mechanism for liver and insulin resistance, as well as the decreased circulating SHBG level are typical for PCOS." (PMID 35140785, 2022). "In our study, hormones like testosterone, sex hormone binding globulin, fasting insulin, and homeostatic model assessment of insulin resistance were significantly higher in the PCOS group compared with non-PCOS group." (PMID 35642189, 2022). "The primary outcomes will be changes in insulin resistance, glucose, total testosterone and sex hormone-binding globulin." (PMID 35448498, 2022). "The reduction of testosterone post-bariatric surgery can be due to increased synthesis of SHBG, which is otherwise inhibited by obesity-related insulin resistance and hyperinsulinemia." (PMID 36045779, 2022). "In its turn, insulin resistance inhibits the liver production of sex hormone-binding globulin (SHBG), which works by binding and sequestering free testosterone, and leads to an increase in circulating testosterone and a further accumulation of abdominal fat." (PMID 36654818, 2022). "In our study, based on the ROC analysis, the empirical optimal SHBG cutoff point for insulin resistance was 41.5 nmol/L." (PMID 35140785, 2022). "Another laboratory test that correlates well with insulin resistance is the concentration of sex hormone binding globulin (SHBG)." (PMID 35885586, 2022). "Obesity causes functional hyperandrogenism among women, irrespectively of PCOS status, mainly by lowering SHBG-production from the liver or increasing insulin resistance, leading to elevated circulating free androgens, also noted in our sample." (PMID 36672604, 2022). "Clustering of variants associated with PCOS has identified three likely etiologic pathways involving adiposity, insulin resistance and SHBG." (PMID 34207127, 2021). "Insulin resistance and hyperinsulinemia contribute to hyperandrogenemia through reducing hepatic production of SHBG, as well as by direct stimulant effects of excess insulin on the ovarian production of androgens by the ovarian theca." (PMID 34063169, 2021). "Hyperinsulinemia resulting from insulin resistance inhibits the hepatic synthesis of sex hormone binding globulin (SHBG) thereby resulting in excess of circulating free androgens." (PMID 34063169, 2021). "In obese patients, hyperinsulinemia that is induced by insulin resistance decreases SHBG secretion by the liver, resulting in greater biological estrogen activity." (PMID 34940598, 2021). "SNPs rs1799941 and rs727428 in the SHBG gene influenced serum SHBG concentrations after controlling for BMI and indexes of androgen excess and insulin resistance." (PMID 34563259, 2021). "This surgery results in reduced BMI and waist circumference, with improved insulin resistance and glucose tolerance, vitamin D, SHBG, FSH and total and free testosterone, inhibin B and AMH, and reduced estrogen and prolactin." (PMID 34829704, 2021). "It has been confirmed that insulin lowers SHBG concentrations in IR generally, and insulin-resistant PCOS specifically." (PMID 34572562, 2021).
Insulin resistance (continued). "They uniformly showed higher insulin resistance, lower SHBG plasma levels, and greater evidence of hyperandrogenism in obese PCOS women compared to their normal weight counterparts." (PMID 33750349, 2021). "Insulin resistance and hyperinsulinemia lower the levels of sex hormone-binding globulin (SHBG), leading to an increase in androgen production." (PMID 34563259, 2021). "The relationship between SHBG levels and insulin resistance is unrelated to estrogen and testosterone levels, and SHBG is closely associated with CVD." (PMID 33918160, 2021). "Insulin resistance results in lower concentrations of sex hormone-binding globulin and consequently increases the bioavailability of sex steroids." (PMID 34947884, 2021). "Obesity is associated with the decreased T level, mediated by the reduced SHBG level due to insulin resistance." (PMID 34225767, 2021). "We decided to perform the experiments using the HepG2 cell line as its well establish a model to study insulin resistance, and what is more, these cells synthetize and secrete SHBG." (PMID 33808055, 2021). "Obesity, low steroid hormone-binding globulin (SHBG), hyperandrogenemia, insulin resistance, and compensatory hyperinsulinemia are biomediators and early predictors of metabolic complications in PCOS." (PMID 34572562, 2021). "Secondly, insulin resistance is described to suppress hepatic sex hormone-binding globulin production and induce ovarian steroid hormone production which result in increased bioavailable estrogen and alleviates the antiestrogen effect." (PMID 34162378, 2021). "The clustering analysis suggests that BMI, insulin resistance, and SHBG are involved in PCOS etiology." (PMID 34207127, 2021). "PCOS women are attributed with increased androgen levels and often present with insulin resistance and compensatory hyperinsulinemia, which inhibits the hepatic synthesis and secretion of SHBG resulting in low circulating SHBG concentrations." (PMID 34563259, 2021). "The SHBG protein level varied largely depending on factors including age, BMI, insulin resistance and liver diseases." (PMID 34207127, 2021). "Experimental studies have shown that hepatic de novo lipogenesis, which is increased in obesity and insulin resistance, impairs SHBG synthesis in the liver." (PMID 34277990, 2021). "Hyperglycemia inhibits hepatic production of Sex Hormone Binding Globulin (SHBG), which leads to an increase of free androgens in the blood circulation, and insulin resistance increases the production of androgens by the theca cells." (PMID 33468143, 2021). "Routine GDM biomarkers (plasma glucose, insulin, C-peptide, homeostatic model assessment of insulin resistance, and sex hormone-binding globulin) can differentiate between healthy pregnant women and those with GDM but are not suitable for early GDM diagnosis." (PMID 34658643, 2021). "Specific TMEs are formed via excess estrogen produced by increased aromatase activity or decreased levels of SHBG, as well as chronic low-grade inflammation in adipose tissues with elevated levels of adipokines and cytokines, leading to insulin resistance." (PMID 32842547, 2020). "This study suggested that SHBG levels plays a more important role in the development of insulin resistance/metabolic syndrome than total or free testosterone does." (PMID 33047895, 2020). "In brief, women with PCOS had increased body weight, higher insulin resistance, and elevated liver enzymes but decreased sex hormone binding globulin." (PMID 33101202, 2020). "It has been shown that insulin resistance promotes the production of male hormones, but lowers the level of sex hormone binding globulin, which leads to a dramatical increase in testosterone level in the body." (PMID 33109277, 2020). "Other authors reported hypertriglyceridemia and insulin resistance in subjects in the lowest quartile of SHBG." (PMID 33396200, 2020).
Insulin resistance (continued). "Because insulin resistance is often accompanied by nutrient oversupply, high dietary intake of monosaccharides can induce low serum SHBG levels through increasing hepatic lipogenesis." (PMID 33139661, 2020). "The research on the mechanisms of PCOS development cannot ignore the influence of inflammatory processes on the development of insulin resistance and the possibility of using SHBG to monitor the course of the disease and as a point of action of new substances." (PMID 32992734, 2020). "Sex hormone-binding globulin is decreased in PCOS patients and appears to be associated with conditions such as hyperinsulinemia and insulin resistance." (PMID 32992734, 2020). "One of the significant PCOS hallmarks interrelated with insulin resistance and HA is a decreased SHBG level." (PMID 32545404, 2020). "Clinical investigations in both boys and girls during puberty have shown that SHBG is a strong predictor of insulin sensitivity and a decline in SHBG predicts the development of insulin resistance." (PMID 33139661, 2020). "In this multiple logistic regression analysis, the optimum model that best explained the presence of testosterone bias included SHBG concentrations (p = 0.002) and insulin resistance (p = 0.033)." (PMID 33352636, 2020). "Although the relationship between SHBG and insulin resistance needs to be further explored, it can be concluded that both insulin resistance and SHBG levels play a crucial role in the changes in serum PSA levels in MetS patients." (PMID 31752806, 2019). "Weight loss results in decrease in cholesterol, triglyceride and LDL levels, improvement in insulin resistance, increase in sex hormone binding globulin and decrease in testosterone levels." (PMID 31423417, 2019). "Secondary outcomes were total and free testosterone, sex hormone binding globulin, and measures of insulin resistance." (PMID 31890686, 2019). "In normal weight women, PCOS is associated with higher prevalence of GDM, a trend towards higher insulin resistance, higher TG and lower SHBG levels." (PMID 31462934, 2019). "The results of the study indicated that insulin resistance and SHBG levels play a important role in the lower serum PSA levels in MetS patients." (PMID 31752806, 2019). "The decrease in serum PSA levels in MetS patients is mainly related to insulin resistance and serum SHBG levels." (PMID 31752806, 2019). "SHBG levels have also been inversely associated with metabolic perturbations that are linked to NAFLD, including insulin resistance, diabetes, and central adiposity." (PMID 32128321, 2019). "Secondary outcomes sought will be free and total testosterone, sex hormone binding globulin and insulin resistance." (PMID 31097035, 2019). "Further research is needed to understand how SHBG is regulated in children and whether sex hormone binding to SHBG or other endocrine factors may underpin the observed associations of SHBG with obesity, insulin resistance and other cardiometabolic risk markers in peripubertal children." (PMID 30925463, 2019). "Hyperinsulinemic insulin resistance acts indirectly on oocyte competence and oocyte quality, increasing the production of ovarian androgens and decreasing the synthesis of hepatic sex hormone-binding globulin (SHBG)." (PMID 29490689, 2018). "Recently, insulin per se was demonstrated not to directly suppress SHBG in vivo, but rather the improvement of insulin resistance elevates SHBG after intensive insulin hypoglycemic therapy." (PMID 30057912, 2018). "In patients with type I diabetes, SHBG levels should be normal or raised; a decrease in SHBG level reflects the emergence of hepatic insulin resistance and therefore is a possible indicator of type II diabetes." (PMID 29995902, 2018). "The insulin resistance leads to decreased hepatic derived circulating sex hormone-binding globulin (SHBG), which in turn increases circulating free estradiol levels." (PMID 29743077, 2018).
Insulin resistance (continued). "Moreover, circulating SHBG was shown to be strongly associated with multiple circulating lipids and metabolites reflecting the degree of adiposity and insulin resistance in men suggesting that low testosterone may be a marker of a metabolic imbalance affecting SHBG production in the liver." (PMID 30057912, 2018). "For instance, SHBG levels were shown to be increased when patients with T2D are treated with rosiglitazone, which reduces insulin resistance by ~30%." (PMID 29995902, 2018). "This highlights a need for further investigation especially as in silico results show they interfere with human sex hormone-binding globulin and increase insulin resistance." (PMID 29891786, 2018). "SHBG metabolism in women therefore sits at the interface between insulin resistance and androgen excess, both key players in PCOS-related metabolic dysfunction." (PMID 29590099, 2018). "Hepatic SHBG output is suppressed by insulin, and therefore, decreased circulating SHBG is a surrogate marker of hyperinsulinemia in the setting of systemic insulin resistance." (PMID 29590099, 2018). "Interventions that reduce weight, ameliorate insulin resistance, fatty liver and lower serum triglycerides lead to increases in serum SHBG." (PMID 29995902, 2018). "We suggest that variation in SHBG reflects de novo lipogenesis within the liver that occurs in the context of insulin resistance." (PMID 29995902, 2018). "Low circulating SHBG levels in childhood and adolescence have been related to hyperinsulinaemia/insulin resistance." (PMID 30321217, 2018). "Epidemiologic and genetic studies have also inferred a role for sex hormone-binding globulin (SHBG) in the pathogenesis of insulin resistance, MetS, and type 2 DM." (PMID 30057912, 2018). "Low levels of serum SHBG are also frequently observed in states of insulin resistance-related conditions and have emerged as a predictor for the incidence of type 2 DM and metabolic syndrome." (PMID 30057912, 2018). "The enhanced insulin resistance in obesity was reflected in the decrease in the SHBG levels particularly in the obese PCOS subjects resulting in an increased FAI." (PMID 28525998, 2017). "Obese patients and those with diabetes or insulin resistance tend to have lower SHBG concentrations and therefore lower serum concentrations of total testosterone." (PMID 28344518, 2017). "The data reported here supported this, with SHBG being significantly lower in women of South Asian origin as a marker of the well-established phenomenon of greater insulin resistance in this group compared with their Caucasian counterparts." (PMID 28458728, 2017). "Secretion is suppressed by insulin, and low levels of SHBG are frequently observed in states of insulin resistance and have been studied as a potential predictor of the development of T2DM." (PMID 28279160, 2017). "Obesity, diabetes and insulin resistance are common reasons for reduced SHBG in HIV patients on treatment, which lowers the serum total testosterone concentration often without affecting free testosterone; weight reduction will correct the binding abnormality." (PMID 28344518, 2017). "In fact, low levels of SHBG have been proposed as a marker of insulin-resistance and hyperglycemia/DM II in patients with AGA13." (PMID 28798373, 2017). "Insulin resistance stimulates insulin release, reduces sex hormone-binding globulin production and increases free testosterone." (PMID 29387827, 2017). "Since the association is independent of many known confounding factors such as obesity, insulin resistance, and lipid disorders, it indicates that the association of SHBG with those metabolic traits is probably a consequence of NAFLD on SHBG levels." (PMID 29109457, 2017). "In obese patients, insulin resistance and hyperinsulinemia can promote androgen secretion and can decrease the level of sex hormone-binding globulin, leading to hyperandrogenemia." (PMID 27686055, 2016).
Insulin resistance (continued). "These participants also had the highest levels of hepatic steatosis, the greatest measured insulin resistance, and the lowest levels of estrogens and SHBG." (PMID 29159307, 2016). "Second, adipose tissue is also related to increased insulin resistance, which lowers sex hormone binding globulin levels leading to increased bioavailability of sex steroids." (PMID 26247479, 2015). "Mechanisms include increasing the pathophysiological factor insulin resistance, which increases hyperandrogenism through augmenting ovarian androgen production and decreasing hepatic production of the androgen binding-protein sex hormone binding globulin." (PMID 26501318, 2015). "Reproductively, insulin resistance increases hyperandrogenism through insulin increasing ovarian androgen production, and reducing sex hormone-binding globulin (SHBG) production." (PMID 26061015, 2015). "Mendelian randomization analyses indicate causal roles in PCOS aetiology for higher BMI (P=2.5 × 10−9), higher insulin resistance (P=6 × 10−4) and lower serum sex hormone binding globulin concentrations (P=5 × 10−4)." (PMID 26416764, 2015). "The variation of SHBG levels is connected with a series of diseases (e.g., polycystic ovarian syndrome, insulin resistance, metabolic syndrome, and osteoporosis)." (PMID 26417369, 2015). "Berberine can also decrease sex hormone binding globulin, insulin resistance, total cholesterol, triglycerides and low-density lipoprotein cholesterol in normal weight polycystic ovary syndrome women." (PMID 26645811, 2015). "Berberine can decrease sex hormone binding globulin, insulin resistance, total cholesterol, triglycerides and low-density lipoprotein cholesterol in normal weight patients with PCOS." (PMID 26645811, 2015). "Sex hormone binding globulin, insulin resistance, total cholesterol, total triglyceride and low-density lipoprotein cholesterol decreased after berberine treatment in the normal weight group only." (PMID 26645811, 2015). "At present, it is believed that the level of SHBG in peripheral blood can reflect the degree of insulin resistance." (PMID 24799941, 2014). "Considering the higher prevalence of insulin resistance in the PCOS women, we analyzed the high risk factors including BMI, testosterone, androgen, SHBG and FAI as the predictors of IR in PCOS women." (PMID 25223276, 2014). "We found a weak inverse correlation between the serum concentration of SHBG and insulin resistance amongst our group of Nigerian men with type 2 diabetes." (PMID 29043159, 2013). "Obese and insulin-resistant men with higher insulin levels would be expected to have lower SHBG levels and consequently lower total testosterone concentrations." (PMID 24391852, 2013). "This study supports earlier observations that a significant, though weak, inverse correlation exists between SHBG and insulin resistance and extends to type 2 diabetic Nigerian men." (PMID 29043159, 2013). "PCOS is characterized by insulin resistance, possibly because of hyperandrogenism and low levels of SHBG." (PMID 23379763, 2013). "The findings in this study are in agreement with their findings, in that we also found an inverse correlation between SHBG and insulin resistance." (PMID 29043159, 2013). "This is one of the first studies to examine the direct effect of sleep restriction on testosterone and sex hormone binding globulin (SHBG), which have both been linked in epidemiological findings with metabolic syndrome and insulin resistance." (PMID 22844441, 2012). "Insulin resistance leads to hyperinsulinaemia, it reduces the SHBG, and it increases the free circulating testosterone, and together hyperandrogenism and hyperinsulinaemia alter the development of the follicles in the ovaries." (PMID 22778733, 2012). "Both low testosterone and sex hormone binding globulin (SHBG) are associated with metabolic syndrome and insulin resistance." (PMID 22844441, 2012).